ZFP36L1 (ZFP36 like 1 zinc finger CCCH-type)
Diseases named in the same sentence as ZFP36L1 in open-access papers (continued):
Sharing a sentence is not in itself a finding about the gene and the disease.
pneumonia (1 paper, 2014). An acute, acute and chronic, or chronic inflammation focally or diffusely affecting the lung parenchyma, caused by an infection in one or both of the lungs (by bacteria, viruses, fungi, or mycoplasma.). "To test our hypothesis that macrophage production of ZFP36L1 is necessary for regulation of the inflammatory response of the lung during pneumonia, we generated mice with a myeloid-specific deficiency of ZFP36L1." (PMID 25299049, 2014). "Furthermore, we hypothesized that a myeloid-specific deficiency of ZFP36L1 would result in elevated levels of lung cytokines and therefore increased efficiency of host defense against pneumonia, but at the cost of increased lung damage." (PMID 25299049, 2014). "In summary, it was unanticipated to find that myeloid deficiency of ZFP36L1 does not appear to be important for the lung's inflammatory response to pneumonia." (PMID 25299049, 2014). "Surprisingly, our investigations demonstrate that, despite its increased production by macrophages in response to pneumonia, myeloid ZFP36L1 alone is not essential for the lung's defense against pneumonia." (PMID 25299049, 2014). "In summary, our data indicated that macrophage ZFP36L1 does not influence antibacterial host defense during pneumonia or sepsis." (PMID 25299049, 2014). "The lack of importance of myeloid ZFP36L1 in the lung's defense against pneumonia is surprising and raises still more questions about the Zfp36 family members and their role in post-transcriptional modification of the inflammatory response." (PMID 25299049, 2014). "Our unanticipated data suggested that myeloid-specific deletion of ZFP36L1 exhibited no impact on select cytokine levels, markers of lung defense, or inflammatory lung injury during pneumonia and sepsis." (PMID 25299049, 2014).
sarcoma (1 paper, 2024). A usually aggressive malignant neoplasm of the soft tissue or bone. "By knockdown and overexpression of ZFP36L1, we found that ZFP36L1 suppressed EMT and metastasis of OS cells, indicating a tumor-suppressing role of ZFP36L1 in sarcoma." (PMID 37935976, 2024). "However, the function of ZFP36L1 in sarcoma remains unknown." (PMID 37935976, 2024).
skin tumor (1 paper, 2021). "It would therefore be important to define the mechanisms leading to decreased ZFP36, ZFP36L1, and ZFP36L2 expression during skin tumor progression." (PMID 33497366, 2021).
tumor (32 papers, 2014 to 2026). "Significantly overexpressed ZFP36L1 in highly malignant tumour cells causes a high accumulation of proliferative and migratory properties in tumour cells." (PMID 38647235, 2024). "In addition to mutations of FGFR3 and KDM6A, we identify ZFP36L1 as a novel, significantly mutated tumor suppressor gene." (PMID 33397444, 2021). "Previous studies have demonstrated the tumor-suppressive role of ZFP36L1 in various cancers, primarily functioning through the binding of target mRNA 3’UTR sequences to accelerate their degradation." (PMID 41285712, 2025). "Small nucleotide polymorphisms (SNPs) were detected in eight genes, and an insertion/deletion was identified in the muscle‐invasive bladder cancer (MIBC) progression‐regulator ZFP36L1 gene in the original BC tumor tissue of the PDX donor." (PMID 40801146, 2025). "ZFP36L1, an RNA-binding protein, suppresses the cell cycle by degrading mRNAs such as Cyclin D1, thereby exerting tumor-suppressive effects." (PMID 41315466, 2025). "ZFP36L1 accelerated tumor progression by mediating JNK and p38 MAPK signaling pathways in gastric cancer." (PMID 38461331, 2024). "Surprisingly, Zfp36l1 is upregulated in Ascl1-OE tumor cells, especially in qNSC and aNSC assigned cell types, likely because it is a target of ASCL1." (PMID 39609428, 2024). "Comparison exclusively between the 19 paired matched samples of tumor and their adjacent normal tissues in TCGA also indicated the low expression of ZFP36L1 in MIBC, even with a less significant difference (p < 0.05, Paired Student’s t-test)." (PMID 35359594, 2022). "The expression of ZFP36L1 is significantly lower in tumor than that in normal tissues among the unmatched MIBC samples in TCGA (408 tumors vs. 19 normal tissues; p < 0.0001, Wilcoxon rank sum test)." (PMID 35359594, 2022). "In the present study, we showed that even though the expression of ZFP36L1 is lower in BC tumor cells than in normal bladder cells, the high expressing level of ZFP36L1 is associated with worse prognosis of BC patients." (PMID 35359594, 2022). "While the tumor-suppressing function of ZFP36L1 was widely reported, results of the survival analysis and GSEA in BC above are needed to be further investigated." (PMID 35359594, 2022). "Consistent with our data above, ZFP36L1 was expressed in the inflammatory tumor cell subpopulation that emerged after cisplatin recurrence while its expression was largely absent in the ASCL1/INSM1-high neuroendocrine populations." (PMID 36008402, 2022). "ZFP36L1 has previously been shown to function as a tumor suppressor in other cancers through its ability to bind AU-rich elements in the 3′UTR of mRNAs leading to mRNA destabilization and tumor suppression." (PMID 36008402, 2022). "Our results are consistent with these studies identifying ZFP36L1 as a tumor suppressor in SCLC, where it also possesses the ability to bind and downregulate mRNAs that promote SCLC neuroendocrine differentiation including INSM1 and SOX2." (PMID 36008402, 2022). "Even though previous studies mostly suggested ZFP36L1 as a tumor-suppressor gene, the results of survival analysis and GSEA assay above raise the attention to the potential cancer promoting effect of ZFP36L1 in MIBCs." (PMID 35359594, 2022). "HIF-1α is recruited to miR-182-5p promoter to transcriptionally upregulate miR-182-5p, which facilitates NPC progression by targeting the tumor suppressor ZFP36L1." (PMID 34465330, 2021). "Thus, ZFP36L1 mutations might lead to an increase in cell migration, bolstering tumor progression." (PMID 33397444, 2021). "A series of functional assays were carried out to evaluate the roles of miR-182-5p and ZFP36L1 in tumor development and progression of NPC." (PMID 34465330, 2021). "Altogether, our study not only identified a new tumor suppressor role of miR-129-5p/ZFP36L1 axis in GBM tumorigenesis, but also provided potential targets for the treatment of GBM patients." (PMID 31999936, 2020).
tumor (continued). "Both TTP and ZFP36L1 have been demonstrated to regulate HIF1α, a member of the family of transcription factors that are the primary effectors of the adaptive response of tumor cells to hypoxia." (PMID 32545247, 2020). "The results of wound-healing assay showed that ZFP36L1 overexpression increased tumor migration ability." (PMID 31999936, 2020). "This study indicated a tumor-suppressor role for ZFP36L1 through regulation of hypoxia, cell cycle, and angiogenesis." (PMID 32545247, 2020). "The present findings revealed a tumor suppressor role of miR-129-5p/ZFP36L1 axis in GBM cell proliferation, migration, and colony-forming ability." (PMID 31999936, 2020). "In vivo studies using ZFP36L1 knockdown (shZFP36L1) or overexpression (oeZFP36L1) 143B cell lines injected into nude mice showed that ZFP36L1 downregulation significantly enhanced tumor survival from MTX treatment." (PMID 41285712, 2025). "ZFP36L1 targets mRNAs involved in tumor progression, such as FGF21, ZEB2, and Cyclin D." (PMID 41285712, 2025). "While our previous research identified ZFP36L1 as a tumor suppressor that inhibits lung metastasis in OS, its role in chemoresistance remains unclear." (PMID 41285712, 2025). "Among the two patients who received R-chemotherapy, one (MC4) gained additional mutations (SELENBP1) in relapse based on pretreatment dominant tumor clones, whereas the other (MC206) acquired mutations (CD70 and ZFP36L1) from a minor and undetected pretreatment tumor clone." (PMID 40876452, 2025). "Many studies have shown that ZFP36L1 suppresses tumor progression." (PMID 37935976, 2024). "Given recent insights linking ZFP36L1 to immune infiltration in tumor microenvironments, these findings suggest that alterations in mitophagy may regulate crucial biological functions." (PMID 38913914, 2024). "Interestingly, the mTOR/MAPKAPK2/4EBP1/ZFP36L1 axis blunts both the pro-tumorigenic the tumour-suppressive effects of the SASP." (PMID 38317146, 2024). "This could lead to combination therapeutic strategies that cooperatively restore ZFP36L1 promoting tumor suppression and increasing tumor immunogenicity." (PMID 36008402, 2022). "Moreover, ZFP36L1 down-regulation was associated with NPC poor prognosis, suggesting the tumor-suppressor role of ZFP36L1 in NPC." (PMID 34465330, 2021). "Furthermore, we identified that ZFP36L1 was the downstream target of miR-129-5p and was responsible for miR-129-5p-mediated tumor proliferation, migration, and colony-forming ability." (PMID 31999936, 2020). "Taken together, these results led to the conflicting roles of ZFP36L1 in regulating the progression of MIBC, and revealed further researches are needed to clarify the functions of the gene in tumor initiation and recurrence." (PMID 35359594, 2022). "Like ZFP36L1, ZFP36L2 has also been indicated to play oncogenic and tumour suppressive roles in different cancer types." (PMID 35008519, 2021). "Overexpression of miR-129-5p in LN229 and A172 cells inhibited the expression of ZFP36L1, while forced expression of ZFP36L1 reversed miR-129-5p-mediated inhibition on GBM tumorigenesis, including tumor proliferation, migration, and colony-forming ability." (PMID 31999936, 2020). "The down-regulated genes included the following: 1) immune system activators such as CD14 and CD1d; 2) hematopoietic tumor suppressor IRF822; and 3) ZFP36L1, a promotor of monocyte/macrophage differentiation that represses CDK623." (PMID 27686215, 2016). "To determine whether the ZFP36L1, SDC4 and p-SMAD3 levels are correlated in OS, we collected 70 patient tumor tissue sections." (PMID 37935976, 2024). "Similar to TTP and ZFP36L1, ZFP36L2 also functions as a tumor suppressor." (PMID 32545247, 2020). "Several of the remaining 21 genes not in the GS, such as MYH14, MED23, and ZFP36L1 in BRCA, and ZNF292, FUBP1, and DTX1 in CLL, had also been implicated in tumor development." (PMID 29030609, 2017).
tumor (continued). "Notwithstanding the lack of tumour suppressor function of ZFP36L1 in the Eμ-Myc mouse model, other studies in human B-lymphoid malignancies have implicated loss of ZFP36L1 function in disease pathogenesis." (PMID 25014217, 2014). "It will be interesting to determine whether non-neuroendocrine “inflammatory” tumor cells with restored ZFP36L1 emerge as a resistance mechanism to LSD1 inhibitors to evade SCLCs inherent neuroendocrine dependence." (PMID 36008402, 2022). "However, under untreated conditions, ZFP36L1 had no discernible effect on tumor growth." (PMID 41285712, 2025). "Moreover, ZFP36, but not ZFP36L1, was shown to function as a tumour suppressor in the Eμ-Myc model." (PMID 25014217, 2014). "ZFP36L1 was also repressed by MYC; however, it was not suggested to be a tumor suppressor in this model." (PMID 32545247, 2020).
cancer (20 papers, 2016 to 2025). A tumor composed of atypical neoplastic, often pleomorphic cells that invade other tissues. "The loss of ZFP36L1 enhances drug resistance, highlighting its potential therapeutic value in cancer treatment." (PMID 41315466, 2025). "We then decided to analyze the frequency of ZFP36L1 mutations in 10,967 cancer samples related to 32 different histopathological cancer subtypes analyzed by TGCA." (PMID 33397444, 2021). "We identified different key findings, including the discovery of novel mutations affecting the zinc-finger RNA-binding protein ZFP36L1 in 20% of cases, a rate by far the highest among cancer subtypes profiled to date." (PMID 33397444, 2021). "Downregulation of ZFP36L1 was considered to be associated with some cancers." (PMID 35359594, 2022). "Also, GSEA indicated that high expression of ZFP36L1 significantly associated with enhanced activity of cancer metastasis related pathways." (PMID 35359594, 2022). "Given that PARP1 inhibitors, which target the SSB repair pathway, have been clinically approved for cancers with DNA repair defects, we further investigated the synergistic effect of ZFP36L1 overexpression with PARP1 inhibitors." (PMID 41285712, 2025). "ZFP36L1, which is a negative regulator of gene transcripts, has been proven to regulate the progression of several carcinomas." (PMID 37935976, 2024). "Among the non-NFκB/TNF hallmark genes that received votes across all 16 cancer types, four genes (SRGN, CCN2, TNFRSF12A, and ZFP36L1) with an average vote exceeding 900 have been reported as regulated by TNF and NFκB." (PMID 37475016, 2023). "Previous identified mRNA targets of ZFP36L1 include mRNAs that drive proliferation in other cancers including Cyclin D, E2F1, and NOTCH29,34." (PMID 36008402, 2022). "In mammals, ZFP36L1 and its family members have been shown to regulate development, cell differentiation, cell cycle, apoptosis and anti-cancer capability by targeting an extensive overlapping repertoire of mRNAs." (PMID 34465330, 2021). "Novel candidate cancer genes include ZFP36L1 and ZFP36L2, which have recently been shown to promote cellular quiescence and suppress S-phase transition during B cell development." (PMID 29056346, 2017). "In this study, we reveal the cancer-inhibitory effect of the RBP ZFP36L1 in OS." (PMID 37935976, 2024). "Indeed, we highlighted three pan-cancer NFκB/TNF hallmark genes (EGR1, JUNB, and ZNF36) and identified four candidates (SRGN, CCN2, TNFRSF12A, and ZFP36L1) that are highly potentially involved in NFκB/TNF pathways in various cancers." (PMID 37475016, 2023). "However, upregulation of ZFP36L1 was also proved to be related to the initiation and progression of cancers." (PMID 35359594, 2022). "We also asked whether ZFP36L1 induction correlates more broadly with LSD1 inhibitor sensitivity across other cancer cell lines." (PMID 36008402, 2022). "To investigate the biology function of ZFP36L1 during cancer progression, we separated MIBCs from TCGA as ZFP36L1High and ZFP36L1low basing on the expression level of ZFP36L1 (top and bottom quartiles, respectively), and performed Gene Set Enrichment Analysis (GSEA) between these two subgroups." (PMID 35359594, 2022). "ZFP36L1 might be a powerful posttranscriptional regulator of cancer." (PMID 37935976, 2024). "The pro-cancer gene HIF1A contains ARE motifs in its 3′UTR, which is critical for ZFP36L1 to directly interact with the 3ʹUTR of HIF1A mRNA and mediate HIF1A mRNA destabilization." (PMID 39547416, 2024). "TTP and its paralogues ZFP36L1 and ZFP36L2 have significant roles in cancer and regulation of the immune system through binding and repressing the expression of mRNAs that contain A/U rich elements." (PMID 37732428, 2023). "While ZFP36L1 and the other TTP members have been found to harbor anti-inflammatory and anti-cancer capability, we have explored the potential involvement of ZFP36L1 in the regulation of aging-related bone loss." (PMID 28206953, 2017).
cancer (continued). "The result suggested the significant down-regulation of ZFP36L1 in superficial and muscle-invasive bladder cancer (MIBC), respectively, and but not in the carcinoma in situ (CIS)." (PMID 35359594, 2022).
infection (16 papers, 2014 to 2025). The state of being infected such as from the introduction of a foreign agent such as serum, vaccine, antigenic substance or organism. "As expected, infection with lenti‐shZFP36L1 reversed the up‐regulation of ZFP36L1 caused by levamisole treatment (d vs c, b vs c)." (PMID 29993187, 2018). "To evaluate whether ZFP36L1 plays a physiological role in limiting cytokine expression during infection we sought to measure cytokine levels in vivo in mice with a deficiency of ZFP36L1." (PMID 25299049, 2014). "This prompted us to test if both ZFP36 and ZFP36l1 are required for T‐cell competitiveness in response to high‐affinity antigens during infection." (PMID 38039407, 2024). "This experiment clearly indicated that ZFP36L1 upregulation upon infection occurred as the result of increased de novo transcription and translation." (PMID 37830871, 2023). "Altogether, these experiments confirmed proteomic data and showed that ZFP36L1 becomes increasingly activated as the infection progresses from virus binding to the inception of latent gene expression." (PMID 37830871, 2023). "We optimized adeno-Cre multiplicity of infection (MOI) based on loss of Zfp36, Zfp36l1, and Zfp36l2 mRNA expression and confirmed loss of ZFP36 and ZFP36L1 protein expression in the adeno-Cre-infected, FBS-stimulated Zfp36/l1/l2 triple-floxed MEFs." (PMID 37086408, 2023). "RT-qPCR-based analysis of transcription showed that the increase in ZFP36L1 protein production is paralleled by a short increase in transcription that reached a maximum at 6 hours post-infection but returned to baseline levels after 2 days." (PMID 37830871, 2023). "Among the proteins identified on the screen, ZFP36L1 (also known as TIS11B or BRF1) was consistently upregulated already at 6 hours post-infection." (PMID 37830871, 2023). "In order to functionally validate ZFP36L1’s role in regulating IL-6 transcript stability upon infection, we knocked down ZFP36L1 expression in primary B cells with a specific siRNA prior to EBV infection." (PMID 37830871, 2023). "This assay showed that VLPs or M81/∆EBNA2 less readily induced ZFP36L1, relative to wild-type infection." (PMID 37830871, 2023). "Cells overexpressing ZFP36L1 or control EGFP were infected with IAV at low multiplicity of infection (MOI = 0.1)." (PMID 32556261, 2020). "Our reverse transcription-polymerase chain reaction (RT-PCR) analysis revealed that ZFP36L1 was specifically upregulated by IL-1β treatment or infection of Ad-HIF-2α or Ad-ZIP8 in primary-culture chondrocytes." (PMID 30622281, 2019). "We used microarray analysis to examine gene expression profiles in primary-culture chondrocytes subjected to knockdown or overexpression of ZFP36L1 via infection of Ad-shZFP36L1 and Ad-ZFP36L1, respectively." (PMID 30622281, 2019). "The lenti-shZFP36L1 infection significantly decreased ZFP36L1 expression as detected by real-time PCR and western blot." (PMID 26542173, 2015). "Compared with lenti-ctrl infection, lenti-ZFP36L1 and lenti-shZFP36L1 infection significantly increased and decreased ZFP36L1 protein level respectively, which led to the remarkable down-regulation and up-regulation of CDK6 expression respectively." (PMID 26542173, 2015). "As expected, re-infection with lenti-CDK6 alleviated the down-regulation of CDK6 expression resulted from lenti-ZFP36L1 treatment (iv versus ii)." (PMID 26542173, 2015). "During an infection time course, ZFP36L1 protein peaked at 2 hours and decreased to baseline between 6 and 24 hours." (PMID 25299049, 2014). "Using macrophage cell lines and primary alveolar macrophages we demonstrated that, like ZFP36, ZFP36L1 is prominently induced by infection." (PMID 25299049, 2014). "Moreover, a knock-down experiment using a specific siRNA showed that downregulation of ZFP36L1 during the first 6 hours of infection led to an increase in IL-6 transcription." (PMID 37830871, 2023). "We also observed a very weak ZFP36L1 induction after M81/∆gp110 infection." (PMID 37830871, 2023).